HIF1A (hypoxia inducible factor 1 subunit alpha)
Diseases named in the same sentence as HIF1A in open-access papers (continued):
Sharing a sentence is not in itself a finding about the gene and the disease.
tumor (continued). "It has also been shown to cooperate with hypoxia-inducible factor 1-alpha (HIF1A) to induce VEGF expression, thus promoting tumor angiogenesis." (PMID 30863721, 2019). "The analysis of a larger independent cohort of 160 HER2‐positive (IHC) tumor specimens selected from TCGA RNA‐seq data set provided additional evidence of a significant correlation between HER2 and HIF1α mRNA levels." (PMID 30132876, 2019). "Recent insights from models of solid tumors in mice with an NK cell specific knockout of the HIF-1α gene and from chemical inhibition of HIF-1α in human NK cells suggest that HIF-1α limits NK cell anti-tumor activity." (PMID 31681292, 2019). "In this report, we revealed that HIF‐1α and ZEB1 in the hypoxic tumor microenvironments would be new potential biomarkers for ACs and then the secondary induced TGF‐β to which EMT induction was dependent would be a critical clinical target for the AC therapy." (PMID 31674718, 2019). "Separately, PER2 has been found to interact with HIF-1α and enhance HIF-1 activity, further demonstrating how circadian proteins can modulate the hypoxic response and therefore alter tumor behavior." (PMID 33089179, 2019). "Considering the hypoxic conditions in the tumor microenvironment and that the primary molecular response to hypoxia is elicited through HIF-1α, we examined HIF-1α expression and found that it was higher in tumor-infiltrating G-MDSCs than in splenic G-MDSCs." (PMID 30925926, 2019). "In tumor cells, MSE is positively correlated with HIF1α, MMP2 and MMP9 expression and thus can reflect the status of the tumor microenvironment." (PMID 31266540, 2019). "We demonstrated that expression of HIF1a and VHL as indicators of ischemia are clearly related to tumour genetics and inflammation in UM, and less to tumour size." (PMID 31323773, 2019). "We have showed that PTBP3 can promote tumor growth, metastasis and angiogenesis, as well as, regulated VEGF expression, which is a direct target of HIF-1A gene." (PMID 31291975, 2019). "To better understand increased HIF1α expression and HIF-responses in tumors of IL27Rα KO mice, we analyzed the number and morphology of tumor blood vessels using immunofluorescence and multi-spectral FACS." (PMID 31637217, 2019). "Due to increased hypoxia in the tumor microenvironment (higher PIM staining), there was also a significant 12-fold (p < 0.0005) and 2.5-fold (p < 0.05) increase in Hif1α and Vegf expression, respectively, in high- versus low-grade TRAMP tumors." (PMID 30813322, 2019). "Hypoxia-inducible factor 1-alpha (HIF-1α) is a transcription factor that mediates adaptive responses to hypoxia and plays important roles in tumor growth and progression." (PMID 31527483, 2019). "Under low oxygen concentrations within the tumor, neoplastic cells and some Tregs express higher levels of CD39 and CD73 in an HIF-1α/mTOR-dependent manner." (PMID 31450598, 2019). "Hypoxia, which is a feature of tumor bearing TME, has a crucial role in stimulating HIF-1α mediated signaling." (PMID 31057536, 2019). "Mechanisms that promote terminal cell differentiation are inhibited via interaction with HIF-1α and NOTCH signaling in PDA and other tumor types." (PMID 30931508, 2019). "As the master regulator during hypoxic responses, HIF-1α is required for the hypoxic regulation of VEGF secretion and tumor angiogenesis." (PMID 30804329, 2019). "To understand further how DBT interfered in molecular pathways of tumor cells, we examined the expression of NF-κB, STAT3, HIF-1α, and VEGF in tumor tissues." (PMID 31781219, 2019). "The clinical pathological variables such as age, tumor size, histological grade, lymph node status, TNM stage, HIF-1α expression, c-myc expression, and Ki-67 expression were included in Cox univariate analysis." (PMID 31577739, 2019).
tumor (continued). "Tumor cells promote angiogenic activity through increases in hypoxia-inducible factor 1α (HIF-1α), vascular endothelial growth factor (VEGF), erythropoietin (EPO), cyclin D1 protein expression, which are essential for tumor growth." (PMID 30678221, 2019). "Hypoxia-inducible factor 1-alpha (HIF1a) and its regulator von Hippel–Lindau protein (VHL) play an important role in tumour ischemia." (PMID 31323773, 2019). "The hazard ratios (HRs) were as follows: lymph node positive (HR = 3.011), histological grade (HR = 2.340), HIF-1α positive expression (HR = 2.027), TNM stage III (HR = 1.632), c-myc-positive expression (HR = 1.514), tumor size > 2 cm (HR = 1.465)." (PMID 31577739, 2019). "PTEN acts as a tumour suppressor gene both by inhibiting the PI3K/Akt pathway, and by acting as a negative regulator of HIF-1α (hypoxia-inducible factor-1)." (PMID 31277414, 2019). "Protein expression studies exhibited that there was a higher expression of HIF-1α in SOR-resistant HepG2/SOR cells and tumor tissues." (PMID 31735093, 2019). "Recently, a few studies have demonstrated the crosstalk between HIF-1α and TGF-β in tumor progression." (PMID 31819036, 2019). "HypoxyprobeTM labeled cells were localized in the perinecrotic (TUNEL+) region of the tumor and co-localized with GFP+ and HIF-1α staining." (PMID 31649238, 2019). "Mechanistically, it was confirmed that tumor-derived TGF-β triggers CD39 and CD73 expression on circulating and tumor-infiltrating MDSCs via activation of mTOR/HIF-1α-signaling." (PMID 31130949, 2019). "This study provides preliminary evidence directing towards the utilization of co-expressional profiles of HIF-1α, MDR1 and LAPTM4B as potential candidate for serum based biomarkers for tumor progression however warranting further clinical surveillance." (PMID 30746305, 2019). "Increased expression of HIF-1α, MDR1 and LAPTM4B was observed with higher tumor stage and distant metastasis (p < 0.05)." (PMID 30746305, 2019). "Hypoxia has been shown to increase autophagy via HIF-1α, which promotes survival of PDA tumor cells, particularly those that are undifferentiated." (PMID 30931508, 2019). "HMGB1 treatment resulted in significant upregulation of stem cell markers (Oct4 and Nanog) and CD133+ cell proportion in fresh tumor tissues, which were abrogated by silencing TLR2, YAP, or HIF-1α." (PMID 31558702, 2019). "Multivariate analysis revealed that for overall survival in GC patients, tumor differentiation and the combined expression of NEDD4L and HIF-1α were independent prognostic factors." (PMID 31673244, 2019). "HIF-1α is the important factor that influences the treatment effect, and the low expression of HIF-1α is very important for preventing tumor recurrence and metastasis after TACE." (PMID 30911540, 2019). "Since HIF1α plays a central role in transcriptional response to hypoxia and ONECUT2 regulates hypoxia signaling and tumor hypoxia, we next sought to characterize the interplay between HIF1α and ONECUT2 at transcriptional regulation." (PMID 30655535, 2019). "Increased HIF1-α, in turn, upregulates the expression of VEGF, FGF or PDGF and increases tumor angiogenesis." (PMID 31370183, 2019). "Upregulation of ectonucleoside triphosphate diphohydrolase (ENTPD2) in HCC cell lines by hypoxia and HIF-1α, contributed to HCC tumour growth and MDSC accumulation." (PMID 31835751, 2019). "HIF-1α promotes the occurrence and development of CRC by increasing the ability of tumor cells to adapt to hypoxia and low energy supply." (PMID 30789971, 2019). "HIF1α activates the transcription of dozens of genes including erythropoietin (EPO), which provide tumor cells with the device to maintain vigorous growth and expansion in a hypoxic microenvironment." (PMID 31752873, 2019).
tumor (continued). "All these results suggest that for the BN4-treated system, hypoxia is induced leading to more tumor growth and more angiogenesis (VEGF, HIF-1α, and GRPR) and more cell proliferation (PCNA and Ki67) that leads to enhanced metastasis of tumor cells." (PMID 30887136, 2019). "In addition, the ARG1 levels can be affected by tumor metabolism; lactic acid produced by tumor cells, a by-product of aerobic or anaerobic glycolysis, up-regulates the levels of ARG1 in tumor associated macrophages by stabilizing hypoxia-inducible factor 1a (HIF1a)." (PMID 30728077, 2019). "The distribution of these markers during tumor progression was as follows: PIMO was the main marker during the early stage (day 3), while HIF-1α and CAIX expression became evident as tumor growth progressed (days 5 to 10)." (PMID 31106146, 2019). "Hypoxic tumor cells can up-regulate the expression of VEGF, and this regulation is closely related to hypoxia-induced specific factor HIF-1α." (PMID 31531063, 2019). "Quantitative analysis of the HIF-1α expression in tumour tissue treated with deoxygenated PNPs showed double the expression observed in tumour tissue treated with ONPs, suggesting that PNPs could actively extract surrounding O2, resulting in long-lasting tumour hypoxia." (PMID 30952842, 2019). "Taken together, the additive and sequential interactions of HIF1α, EGR1 and SP1 finely mediate EPO-R expression in NSCLC under hypoxia, which affects NSCLC progression and makes it response sensitively to the tumor microenvironment." (PMID 31752873, 2019). "TNuF was experimentally shown to suppress metastasis of tumor cells and expression of tumor-induced VEGF as well as expression of EGFR, HIF-1α and CD31 in lung tissues." (PMID 31426614, 2019). "Hypoxia-inducible factor 1α (HIF-1α) mediates expressions of VEGF and EPO, important factors that involve tumor angiogenesis." (PMID 30678221, 2019). "Our results proved that silence of ATG5 enhanced the positive wound healing and inhibited metastatic spread of tumor cells, finally indicating downregulation of ATG5 alleviates HIF1α-induced metastasis in PCa." (PMID 31700698, 2019). "In the liver, hypoxia-derived HIF-1α induces changes in surface and soluble MHC class I polypeptide-related sequence A (MICA), thus impairing NK cell’s ability to recognize the tumor." (PMID 31450598, 2019). "HIF-1α is also known to mediate the expression of vascular endothelial growth factor (VEGF) and promote aggressive tumor growth." (PMID 31470659, 2019). "At the same time, the formation of lactic acid from pyruvate is facilitated by the HIF-1α-mediated upregulation of LDHA, which contributes to the acidification of the tumor microenvironment." (PMID 31078780, 2019). "It downregulated the protein expression of HIF-1α and the expression of HIF target genes: vascular endothelial growth factor (VEGF) and erythropoietin, essential for tumor growth." (PMID 31547375, 2019). "Then, it was shown that BNIP3 is essential for hypoxia-induced autophagy in cancer cells and disruption of BNIP3 triggered cell death, which suggests a positive role of HIF-1α, BNIP3, and autophagy in tumor survival and progression." (PMID 31078780, 2019). "In HCC, sorafenib aggravates microenvironmental hypoxia while exerting anti-tumor effects and then induces the enhancement of CSC properties by activating HIF-1α, which leads to drug resistance." (PMID 31341646, 2019).
tumor (continued). "Accordingly, expression of HIF-1α, Nanog and OCT4 has been observed in primary PCa tumors, of which, expression of Nanog and OCT3/4 were highly enriched in HIF-1α positive tumor regions." (PMID 30842790, 2019). "Hypoxia inducible factor-1α (HIF-1α) and hypoxia inducible factor-1β (HIF-1β) are under hypoxic conditions, and the expression will be increased when tumor and normal cells is under hypoxic stress." (PMID 31391918, 2019). "In cancer cells, c-Myc increases the transcriptional level of HIF-1α, thus increasing the expression of HIF-1α, further promoting the expression of VEGF, which participates in downstream signaling pathways and promotes tumor angiogenesis." (PMID 31309249, 2019). "The elevated expression of HIF-1α, MDR1 and LAPTM4B was found to be correlated with advanced tumor stage and metastasis (p < 0.05)." (PMID 30746305, 2019). "Tumours with monosomy 3 (M3) (n = 34) had a higher expression of HIF1a (p = 0.001) and a lower expression of VHL (p < 0.001) compared to tumours with disomy 3 (D3) (n = 20)." (PMID 31323773, 2019). "Cox univariate analysis showed tumor size, histological grade, lymph node status, TNM stage, HIF-1α expression, and c-myc expression were the factors influencing postoperative survival in TNBC patients." (PMID 31577739, 2019). "Within the set of D3 tumours, BAP1-negative tumours (n = 3) had a higher expression of HIF1a compared to BAP1-positive tumours (n = 17, p = 0.028)." (PMID 31323773, 2019). "In a HNSCC heterotopic xenograft tumor model, treatment with the epidermal growth factor receptor (EGFR) blocker Cetuximab inhibits angiogenesis by downregulating Notch1 and Hypoxia-inducible factor 1 alpha (Hif1α) subunit." (PMID 30917608, 2019). "It has been found that hypoxic regions of TME promote CSC enrichment via upregulation of HIF-1a activity, and TME stiffness affects YAP signaling of tumor cells." (PMID 31394796, 2019). "Hypoxia-inducible factors including HIF1α in the tumor microenvironment trigger both stemness and EMT programs in the tumor, while impairing DC mediated anti-tumor immunity." (PMID 31921140, 2019). "Among the most commonly altered of the regulatory genes that are involved in cellular metabolism were PIK3CA (in 32% of tumours), MYC (in 14%) and HIF1A (in 11%)." (PMID 31754644, 2019). "Clinically, high levels of HIF-1α and HIF-2α positively correlate with tumor progression and poor patient outcome." (PMID 30642030, 2019). "It has been shown that under hypoxic conditions, LCN2 expression is increased at HIF-1α-positive regions of tumors and parallels HIF-1α expression in those tumor cells." (PMID 30871254, 2019). "In normoxic conditions, deletion of HIF-1α (blue) results in fewer lung tumours, whereas deletion of HIF-2α (orange) leads to increased tumour burden (left)." (PMID 31308473, 2019). "Since the elevated oxygenation decreases HIF-1α expression, the downstream factor VEGF would be inhibited to restrict tumor angiogenesis and deterioration." (PMID 31695774, 2019). "HIF-1α-positive cells spread in the whole tumor area to the tumor periphery in the CXCR4-inhibited group, whereas HIF-1α-positive cells were limitedly localized in the central area of tumors in the control group." (PMID 31336612, 2019). "Another unfavorable aspect of TACE for high tumor burden HCC is that incomplete TACE increases tumor hypoxia, leading to the upregulation of hypoxia inducible factor-1-α (HIF1-α)." (PMID 31370183, 2019). "Immunohistochemistry was performed to measure the expression of HIF-1α, LDHA and CD31 in tumor tissues." (PMID 31455352, 2019). "Studies have shown that HIF-1α induces P4HA1 expression in a hypoxic microenvironment, and P4H can regulate cell metabolism and enhance the activity of tumor cells." (PMID 31711497, 2019). "The PI3K/Akt/mammalian target of rapamycin (mTOR) and ERK pathways control the translation of HIF-1α, and HIF-1α activates VEGFs, u-PA, and MMP-2 and -9 to promote tumor metastasis." (PMID 31041568, 2019).
tumor (continued). "We demonstrated that both HIF1a and VHL are strongly related to tumour genetics, and wondered how this related to tumour size." (PMID 31323773, 2019). "Simultaneously, we assessed the levels of other certain molecular markers, such as HIF-1α and GRP-78, which are correlated with tumor progression in several types of cancer." (PMID 30804322, 2019). "In low oxygenated cells, HIF-1α, mTOR, TGFβ and Stat3 levels were shown to increase CD133 expression in tumour cells, promoting GSC formation and proliferation." (PMID 31690341, 2019). "In conclusion, our study demonstrates that low expression of CDK5RAP3 in GNEC activates the AKT/HIF-1α/VEGFA signaling pathway, increasing secretion of VEGFA from GNEC cells into the tumor microenvironment and promoting tumor angiogenesis." (PMID 31728130, 2019). "At the same time, GBEE down-regulated the expression of HIF-1α, VEGF and VEGFR2 in B16 transplanted tumor." (PMID 31531063, 2019). "When HIF-1α is knocked out, increased fatty acid catabolism improves peroxisome proliferator-activated receptor α signaling in CD8+ tumor-infiltrating lymphocytes." (PMID 31519198, 2019). "At the molecular level, tumor cell adaptation to hypoxia is regulated in part by the PI3K/AKT/mTOR pathway and by the transcription factors HIF-1α and HIF-2α, whose protein expression and transcriptional activity are also partly regulated by mTOR." (PMID 31627299, 2019). "HIF-1α and HIF-2α were elevated in both pRCC and ccRCC tumor types compared to kidney cortex tissue with the difference reaching significance in ccRCC (p < 0.001)." (PMID 30555801, 2018). "Similar gene expression levels of HIF-1α and CREB were observed between the tumor cell lines (HT29 and B16F10 cells) and normal cell lines (HUVECs and HEK293 and Balb3T3 cells), but HT29 cells had higher expression levels of NF-κB than HEK293 cells and HUVECs." (PMID 29703163, 2018). "Increased T cell function was observed after incubation of T cells in preconditioned media from tumor cells treated with MSA, an effect that was coupled to decreased levels of PDL1, HIF-1α, and VEGF." (PMID 30324091, 2018). "We also found that HIF-2α downregulation sensitized GBM cells to cisplatin more effectively than HIF-1α downregulation, substantiating the differential roles of HIF-1α and HIF-2α in tumour development." (PMID 29492900, 2018). "HIF-1α can mediate VEGF expression, and VEGF is an important factor in promoting angiogenesis and participating in tumor angiogenesis." (PMID 29531823, 2018). "We illustrated that intratumoral vascular pruning induced by VEGF Ab resulted in hypoxia, HIF-1α nuclear accumulation, MET activation and conversion to a more mesenchymal tumor cell phenotype." (PMID 29712569, 2018). "We propose that DKG acts as a potent HIF-1α activator, highlighting the potential use of DKG to investigate the contribution of the PHD2-HIF-1α pathway to tumor biology." (PMID 29402287, 2018). "The overexpression of the Trx1 gene activated hypoxic induction factor 1 (HIF-1α) in cancer cells, increasing VEGF expression and promoting tumour angiogenesis, which leads to tumour invasion and metastasis." (PMID 30454068, 2018). "HIF-1α and HIF-2α have opposing effects in ccRCC biology, with HIF-1α acting as a tumor suppressor and HIF-2α acting as an oncogene." (PMID 29357946, 2018). "A homolog of HIF-1α, HIF-2α, has been shown to be expressed at more moderate hypoxic conditions, and stimulates tumour cell proliferation, invasion, and stemness." (PMID 29382042, 2018). "Tumor-derived exosomal miR-23a directly suppressed the expression of prolyl- hydroxylase 1 and 2 (PHD1 and 2), leading to the accumulation of HIF-1α in ECs and increased angiogenesis." (PMID 29415727, 2018).